CSF3R (colony stimulating factor 3 receptor)
Diseases named in the same sentence as CSF3R in open-access papers (continued):
Sharing a sentence is not in itself a finding about the gene and the disease.
leukemia (26 papers, 2015 to 2025). A malignant (clonal) hematologic disorder, involving hematopoietic stem cells and characterized by the presence of primitive or atypical myeloid or lymphoid cells in the bone marrow and the blood. "Acquired somatic mutations in CSF3R, the gene encoding G-CSFR, have been found in a variety of leukemias." (PMID 36703974, 2022). "The zebrafish csf3r gene was targeted with CRISPR-Cas9 to generate truncating hyperresponsive G-CSFR mutations based on those observed in leukemia." (PMID 36703974, 2022). "Analyses of extensive family pedigrees would be required to assess leukemia predisposition based on CSF3R truncations, a resource which is unavailable." (PMID 35200567, 2022). "Molecular events that lead to clonal evolution and malignant transformation include acquired mutations in the CSF3R gene (encoding the G-CSF receptor) and subsequently in other leukemia-associated genes (such as RUNX1)." (PMID 33802366, 2021). "Taken together, our results support the following proposed mechanism for leukemia development in CN: CSF3R mutations represent a state of clonal hematopoiesis of indeterminate potential (CHIP) in CN patients in that they confer a clonal advantage." (PMID 32821971, 2020). "Patients with SCN reportedly have a 21% cumulative incidence of myeloid malignancy after 10 years with the risk of leukemia being higher in patients requiring high doses of G-CSF, and is associated with acquired mutations in CSF3R and RUNX1." (PMID 32066420, 2020). "In the present study, we sought to establish an in vitro experimental model to study the intracellular mechanisms of leukemia development downstream of CSF3R and RUNX1 mutations." (PMID 32821971, 2020). "Intriguingly, there is a high incidence of transformation to myelodysplasia (MDS) or acute myeloid leukemia (AML) in patients who harbor acquired CSF3R mutations, suggesting that these mutations are involved in the development of leukemia." (PMID 30891028, 2019). "This approach enables the identification of low-frequency CSF3R mutant clones, increases sensitivity, and earlier detection of CSF3R mutations acquired during the course of leukemogenic evolution of pre-leukemia HSCs of CN patients." (PMID 30891028, 2019). "We have shown in this report and in earlier studies that ~80% of CN patients who developed leukemia harbor acquired CSF3R mutations, and that all leukemic cells in these patients are affected by these mutations." (PMID 30891028, 2019). "The combination of mutations produced maturation arrest, similar to CSF3R/CEBPA mutant murine leukemia." (PMID 31784538, 2019). "The time between acquisition of CSF3R mutations and overt leukemia vary substantial, some patients carry CSF3R mutations for more than 10 years." (PMID 30891028, 2019). "CSF3R mutations are considered drivers of leukemia and have been found in patients with aCML." (PMID 38992589, 2024). "Next generation sequencing of the leukemia cells identified CSF3R and RUNX1 mutations." (PMID 35846055, 2022). "Moreover, the integration of genomic and functional analyses yielded cancer driver mutations in the CSF3R gene in leukemia and identified small molecule kinase inhibitors targeting CSF3R downstream signaling pathways." (PMID 34729943, 2021). "Point mutations in the colony-stimulating factor 3 receptor (granulocyte) (GCSFR or CSF3R) gene are seen in bone marrow cells from most SCN patients who develop leukemia, suggesting that such mutations are highly predictive, although not essential, for malignant transformation in these subjects." (PMID 27703456, 2016). "Additionally, CSF3R mutations are implicated in leukemic transformation from severe congenital neutropenia, which is typically acquired early and followed by mutations in leukemia‐related genes such as RUNX1, suggesting stepwise clonal evolution." (PMID 41423432, 2025). "CSF3R’s recently emerging role in leukemia prompted us to investigate the genetic alterations of this gene in our B-ALL cohort." (PMID 34573308, 2021).
leukemia (continued). "Genetic alterations in the CSF3R gene have been reported recently in different leukemias of myeloid and lymphoid origin." (PMID 34573308, 2021). "Elucidation of the deregulated intracellular signaling pathways downstream of CSF3R and RUNX1 mutations will help to identify druggable targets, with the goal of eliminating leukemia-predisposed HSPCs and/or specifically targeting CN/AML blasts." (PMID 32821971, 2020). "The identification of cooperative CSF3R and RUNX1 mutations in a majority of CN patients with overt MDS or AML brought us one step closer to understanding leukemia development." (PMID 32821971, 2020). "We next sought to establish whether a CSF3R germline truncation mutant could be involved in setting the stage and contribute to predisposition for CNL and leukemia development." (PMID 35200567, 2022). "Somatic mutations in CSF3R leading to truncated G-CSFR forms are observed in acute myeloid leukemia (AML), particularly those subsequent to severe chronic neutropenia (SCN), as well as in a subset of patients with other leukemias." (PMID 36703974, 2022). "The presence of these mutations may predispose to acquisition of secondary mutations in CSF3R and RUNX1 and the development of leukemia." (PMID 32821971, 2020). "Furthermore, they proved that both proximal and compound CSF3R mutations relied on enhanced MAPK signaling for oncogenic transformation and effectively abrogated leukemia development in mice expressing either of these mutational variants by targeting Mek1/2 with Trametinib123." (PMID 29440636, 2018). "While all cells remained CD11b+, solely leukemia cells expressing both STAT3 isoforms responded to G-CSF by notable upregulation of the granulocytic surface marker Gr-1, while on the mRNA level expression of the G-CSF receptor (Csf3r) was comparable in suspension culture." (PMID 38806478, 2024).
acute myeloid leukemia (22 papers, 2010 to 2025). Acute myeloid leukemia (AML) is a group of neoplasms arising from precursor cells committed to the myeloid cell-line differentiation. "Activating colony‐stimulating factor 3 receptor (CSF3R) mutations are uncommon in acute myeloid leukemia (AML), and their prognostic significance remains unclear." (PMID 41423432, 2025). "RUNX1 and CSF3R are frequently co-mutated in the progression to acute myeloid leukemia from SCN." (PMID 35200567, 2022). "This study aimed to elucidate the clinical and prognostic relevance of CSF3R mutations in acute myeloid leukemia (AML), with a particular focus on their molecular characteristics, treatment responses, and survival outcomes." (PMID 41423432, 2025). "This investigation aims to assess the impact of CSF3R mutations and the presence of measurable residual disease(MRD)on the prognosis of patients with CEBPA double mutations who have acute myeloid leukemia(AML)." (PMID 36709108, 2022). "Two concurrent mutational signatures in CSF3R (Colony Stimulating Factor 3 Receptor) and CEBPA (CCAAT Enhancer Binding Protein Alpha) that are related to higher relapse rates have been identified in patients with acute myeloid leukemia." (PMID 36295546, 2022). "CSF3R expression is positively related to prognosis in patients with acute myeloid leukemia." (PMID 33371790, 2021). "Alterations in CSF3R are also infrequently associated with other myeloid neoplasms, such as chronic myelomonocytic leukemia (CMML), myelodysplastic neoplasms (MDS), or acute myeloid leukemia (AML)." (PMID 40806796, 2025).
chronic myeloid leukemia (14 papers, 2019 to 2025). "In atypical chronic myeloid leukemia (aCML), characterized by dysplastic neutrophils and circulating precursors, CSF3R mutations have been found in ~18% of cases." (PMID 41154433, 2025). "Tumor samples of BRCA exhibited lower retention of intron 3 in CSF3R, which is a highly mutated oncogene in chronic myeloid leukemia." (PMID 38067392, 2023). "This is particularly the case for mutations in CSF3R commonly present in chronic neutrophilic leukaemia or atypical chronic myeloid leukaemia." (PMID 35860558, 2022). "Given the roles of CSF3R reported in chronic neutrophilic leukaemia or atypical chronic myeloid leukaemia, our findings suggest that CSF3R might play a pivotal role in the occurrence and development of SCLC." (PMID 35860558, 2022). "After an initial diagnosis of chronic myeloid leukemia, the patient’s clinical course was shaped by hematologic toxicity, the emergence of treatment-resistant BCR-ABL1 clones, and the expansion of a CSF3R-mutant clone without ABL1 mutations under selective pressure from tyrosine kinase inhibitors." (PMID 33516272, 2021).
myeloid neoplasm (12 papers, 2016 to 2025). Proliferation of myeloid cells originating from a primitive stem cell. "Given the rarity of CSF3R-mutated myeloid neoplasms outside of CNL and aCML, our cohort represents one of the largest institutional case series described to date." (PMID 40806796, 2025). "Our study provides valuable insights into the genetic landscape of CSF3R-mutated myeloid neoplasm and adds to the growing body of evidence that CSF3R mutations, especially T618I, are a critical component of the molecular landscape beyond CNL, aCML, and SCN." (PMID 40806796, 2025). "From a practical standpoint, while CSF3R mutations are rare in myeloid neoplasms outside of CNL and aCML (~0.9% in our series), they remain clinically actionable." (PMID 40806796, 2025). "We identified thirteen (0.9%) with CSF3R-mutated myeloid neoplasms, which were categorized into three diagnostic groups." (PMID 40806796, 2025). "Here, we analyzed a large cohort of myeloid neoplasms to evaluate the incidence of CSF3R mutations and co-mutational profile." (PMID 39907800, 2025). "The mutational landscape across the 13 patients with CSF3R-mutated myeloid neoplasms was highly heterogeneous." (PMID 40806796, 2025). "In the current study, we performed mutational analysis using targeted next-generation sequencing (NGS) in a consecutive cohort of 360 patients diagnosed with myeloid neoplasms, to identify mutations in CSF3R gene in different subgroups." (PMID 39907800, 2025). "The altered CSF3R expression or activating heterozygous variants in CSF3R have been identified as risk factors in the development of multiple malignancies, such as colorectal cancer, myeloid malignancies and lymphoid malignancies." (PMID 35860558, 2022). "Because of the potential benefit of ruxolitinib in CSF3R T618I mutated myeloid neoplasms, the patient was commenced with an off-label prescription of ruxolitinib with a dose of 10 mg twice daily (day 0)." (PMID 32660441, 2020). "Notably, the JAK1/2 inhibitor ruxolitinib has shown efficacy in patients with CSF3R T618I‐positive CNL and anecdotal benefit in other CSF3R‐mutated myeloid neoplasms." (PMID 41423432, 2025). "This diversity in mutation percentages highlights the complex clonal architecture of CSF3R-mutated myeloid neoplasms and emphasizes the importance of considering the broader mutational context when interpreting the role of CSF3R in disease pathogenesis and therapeutic decision-making." (PMID 40806796, 2025). "Furthermore, trametinib was found to play a role in targeting the MAPK signaling pathways in myeloid malignancies associated with wild or truncated CSF3R mutations that fail to activate MEK/extracellular-signal-regulated kinase (ERK) signals." (PMID 35949766, 2022). "Although CSF3R genetic alterations may belong to three different classes, the point mutation T618I, affecting the transmembrane proximal domain, is the most common pathogenic alteration in myeloid neoplasms." (PMID 40806796, 2025). "A CSF3R gene mutation was present in 13/179 AML cases (7.3%), in 2/27 (7.4%) CMML cases, in 1/94 (1.1%) MDS cases and in 4/60 (6.7%) other myeloid neoplasms." (PMID 39907800, 2025). "Other myeloid neoplasms, including MDS, showed low-frequency CSF3R mutations (≤10%), suggesting a smaller subclonal role." (PMID 40806796, 2025). "All these factors make the identification of myeloid neoplasms with CSF3R alteration clinically relevant." (PMID 40806796, 2025). "CNL can also arise from different myeloid neoplasms; a recent case report showed a patient who was diagnosed with MDS with U2AF1 and SETBP1 mutations who, 3 years later, developed CNL and acquired CSF3R and ASXL1 mutations." (PMID 39858009, 2025).
myeloid neoplasm (continued). "The co-occurrence of U2AF1 and signaling gene mutations also differed across myeloid neoplasms, with NRAS and FLT3 mutations being more common with S34 mutations and CBL, PTPN11 and CSF3R mutations more common with R156/Q157 mutations." (PMID 40386435, 2025). "Other myeloid neoplasms displayed intermediate VAFs (median, 12%; range, 2–24%), indicating a smaller contribution of CSF3R to disease pathogenesis." (PMID 40806796, 2025). "In our cohort of thirteen patients, we identified CSF3R alterations across a variety of myeloid neoplasms, including MDS/MPN-U, AML, MPN with disease progression, MPAL, CMML, and MDS-IB1, suggesting a broader role for CSF3R in pathogenesis of myeloid neoplasms and clonal evolution." (PMID 40806796, 2025).
chronic myelomonocytic leukemia (10 papers, 2014 to 2025). A myelodysplastic/myeloproliferative neoplasm which is characterized by persistent monocytosis, absence of a Philadelphia chromosome and BCR/ABL fusion gene, fewer than 20 percent blasts in the bone marrow and blood, myelodysplasia, and absence of PDGFRA or PDGFRB rearrangement. "In adult and pediatric acute myeloid leukemia about 0.5 to 1% and about 2 % harbor a CSF3R mutation, respectively, and in chronic myelomonocytic leukemia (CMML) about 4% show such a mutation." (PMID 34298741, 2021). "In chronic myelomonocytic leukemia (CMML), CSF3R mutations occur at an even lower frequency of <2%, with these associated with poorer outcomes." (PMID 41154433, 2025).
myeloproliferative disorder (10 papers, 2014 to 2025). A clonal hematopoietic stem cell disorder, characterized by proliferation in the bone marrow of one or more of the myeloid (i.e., granulocytic, erythroid, megakaryocytic, and mast cell) lineages. "The authors suggested that mutations in the CSF3R gene might be responsible for hereditary neutrophilia mimicking a myeloproliferative disorder." (PMID 25431700, 2014). "The emergence of the CSF3R-mutant, neutrophilic clone led to the diagnosis of CNL as a second myeloproliferative neoplasm in the same patient." (PMID 33516272, 2021).
colorectal cancer (7 papers, 2014 to 2025). A primary or metastatic malignant neoplasm that affects the colon or rectum. "CSF3R significantly correlates with a large number of genes that are associated with poor colorectal cancer prognosis." (PMID 33606788, 2021). "Similarly, CSF3R plays a dual role in CD and colitis-associated colorectal cancer (CAC)." (PMID 40918404, 2025). "We utilized publicly available datasets to guide future mechanistic studies of the role CSF3 and its receptor (CSF3R) play in colorectal cancer development and progression." (PMID 33606788, 2021). "Another research team studied the CSF3/CSF3R signaling in colon and rectal cancers, and results indicated that CSF3/CSF3R expression was correlated with changes in T cell and macrophage signatures and also correlated with genes that are associated with poor colorectal cancer prognosis." (PMID 34729112, 2021).
myeloproliferative neoplasm (7 papers, 2019 to 2025). "Chronic neutrophil leukemia (CNL) is a rare BCR/ABL-negative myeloproliferative neoplasm (MPN) whose molecular biology is based on mutations in the CSF3R (Colony Stimulating Factor 3 Receptor)." (PMID 39105740, 2024).
plasma cell dyscrasia (7 papers, 2018 to 2024). "The improvement in this patient's neutrophilia and CSF3R mutation VAF with RCD chemotherapy are promising signs, and further research is required to understand whether this regimen could play a role as a future treatment in patients with both CNL and plasma cell dyscrasia." (PMID 35898175, 2022). "However, in this case, the presence of the CSF3R mutation indicates there are two distinct diagnoses in play, namely CNL and a plasma cell neoplasm, rather than merely a reactive neutrophilia driven by abnormal plasma cells, and this is a more unusual finding." (PMID 35898175, 2022).